ENO1 (enolase 1)
Diseases named in the same sentence as ENO1 in open-access papers (continued):
Sharing a sentence is not in itself a finding about the gene and the disease.
tumor (continued). "ENO1 is a multifunctional protein with oncogenic properties, as it was shown to drive the progression of various cancer types by promoting tumor cell proliferation, migration, and invasion." (PMID 40775002, 2025). "CRISPR-Cas9-mediated knockout of ENO1 and ENOblock reduced tumor burden and promoted infiltration of cytotoxic CD8+ T cells." (PMID 41373732, 2025). "Stabilization of ENO1 was associated with enhanced aerobic glycolysis and ERK signaling, thereby facilitating tumor growth and metastatic potential." (PMID 41514569, 2025). "A heatmap of RNA-seq showed that most of interleukin family and chemokine family were upregulated in ENO1-KO tumor tissues." (PMID 40665335, 2025). "Combined inhibition of TLR4 and SPHK1 synergizes with TMZ to suppress tumor growth and reverse M2 macrophage polarization in vivo, highlighting the therapeutic promise of targeting the ENO1/TLR4-SPHK1 axis." (PMID 41353343, 2025). "This study investigated the expression of two potential biomarkers—Inter-Alpha-Trypsin Inhibitor Heavy Chain 2 (ITIH2) and Enolase 1 (ENO1)—in the mammary glands of healthy and tumor-bearing dogs using immunohistochemistry." (PMID 40005870, 2025). "AL355338 is an oncogenic lncRNA upregulated in NSCLC that binds to and stabilizes ENO1, therefore enhancing glycolysis and driving tumor progression via the EGFR/AKT signaling pathway." (PMID 41361062, 2025). "This antigen is ENO1, previously defined as a moonlight protein due to its multiple locations and functions in supporting tumour metabolism, growth, survival and invasiveness." (PMID 40831074, 2025). "Mechanistically, ENO1 regulated CD8+ T cell function and tumor-associated macrophage (TAM) polarization via the SPP1-ITGA4/ITGB1 pathway in the TME." (PMID 40665335, 2025). "ENO1 is involved in multiple tumor-related biological processes, such as growth, metastasis, and resistance to treatment." (PMID 40665335, 2025). "IHC staining of post-treatment intracranial tumor sections quantified the expression of M2 macrophage markers ENO1, CD163, and phosphorylated SPHK1 (p-SPHK1)." (PMID 41353343, 2025). "Flow cytometry and mIHC corroborated the enhanced production of IFN-γ and GZMB in tumor-infiltrating CD8+ T cells from ENO1-KO samples." (PMID 40665335, 2025). "The significantly increased levels of ENO1 mRNA were found in tumor versus non-tumor tissues in the TCGA data." (PMID 40573960, 2025). "Functional validation demonstrated that ENO1/PGM2L1 co-expression promoted tumor proliferation, migration, invasion, and glycolytic flux in vitro, while accelerating xenograft growth in vivo." (PMID 40507914, 2025). "Firstly, ENO1 expression was elevated in the tumor group and significantly higher in aging T cells compared to the young group." (PMID 39457014, 2024). "ENO1 promotes glycolytic metabolism, oncogenic signaling, tumor migration, invasion, and metastasis." (PMID 38840205, 2024). "First, we examined the mRNA levels of PKs and ENOs, and found that PKM and ENO1 were the predominantly transcribed genes of these two families in tumor cells, that encodes PKM1, PKM2 and ENO1." (PMID 38750259, 2024). "Further, AGTR1 is also involved in regulating immune chemokines, checkpoints and immune regulatory factors such as PECAM1, ADARB1, SPP1 and ENO1, all of them playing important roles in immune cell regulation, tumor cell proliferation and migration." (PMID 39450258, 2024). "α-Enolase (ENO1) is a crucial molecular target for tumor therapy and has emerged as a research hotspot in recent decades." (PMID 38273010, 2024). "The glycolytic function of ENO1 is involved in relieving cell energy regulation, maintaining tumor proliferation, and inhibiting apoptosis of cancer cells." (PMID 39450258, 2024). "Collectively, our study not only demonstrated that inhibiting cell senescence is an effective anti-skin photoaging strategy, but also revealed that ENO1 is a promising protein target to prevent photoaging." (PMID 39741388, 2024).
tumor (continued). "ENO1 can also induce regulatory T cells (Tregs) to promote cancer development by suppressing anti-tumor immune responses." (PMID 39450258, 2024). "A low-to-moderate positive correlation was observed between ENO1 expression and certain tumour-infiltrating lymphocytes (TILs), immunomodulators, and chemokines, whereas a negative correlation was observed with ENO1 methylation." (PMID 39483155, 2024). "Although genomic alterations of ENO1 in BC are rare, an increased rate of ENO1 alterations in metastatic tumours as compared with primaries was identified, indicating that ENO1 alterations accumulate with progression and treatment." (PMID 39483155, 2024). "Considering that ENO1 was highly expressed in tumor cells and positively correlated with malignant phenotypes, we performed further analysis of epithelial cells (ECs) in the scRNA-seq data." (PMID 38273010, 2024). "The expressions of CyclinE1, ERBB2, and ENO1 in the tumor were inhibited by PP in vivo, consistent with that observed in vitro." (PMID 39576845, 2024). "For HCC, Alpha-enolase (ENO1) is an essential enzyme for glycolysis that contributes to the lactic acid production in tumor cells." (PMID 39227992, 2024). "Considering that inflammation is one of the critical factors for the initiation of tumor development and progression, IL-32 production by ENO1 stimulation is closely related to tumorigenesis." (PMID 38675491, 2024). "TCGA database was used to assess the correlation between tumor immune cell infiltration and ENO1 gene expression." (PMID 39576845, 2024). "Tumours with ENO1 deletion become reliant on ENO2 for glycolysis and are thus prone to synthetic lethality when ENO2 is pharmacologically targeted." (PMID 38473245, 2024). "They found four autoantigens, including ENO1, with significantly greater immunoreactivity in tumor samples than in normal samples, which were identified as biomarker candidates." (PMID 39061201, 2024). "And ENO1 can promote tumor cell proliferation and alter the phosphatidylinositol 3-kinase/Akt signaling pathway between cells, mediating drug resistance." (PMID 38840205, 2024). "Proliferation, and cytokine release and TCRB repertoire of from PDA patient peripheral T lymphocytes, before and after CT, were analyzed in vitro in response to four tumor-associated antigens (TAA), namely ENO1, FUBP1, GAPDH and K2C8." (PMID 39176093, 2024). "ENO1 enhances tumor-related cellular activities such as increased glycolysis, cancer cell proliferation, migration, invasion, drug resistance, and oncogenic signaling pathway activation." (PMID 38643300, 2024). "Consistent with our findings, higher ENO1 protein expression in DLBCL patients’ tumor tissues indicated poorer survival." (PMID 38840205, 2024). "As an example of the power of the combination of the two data sets produced, we found a genetic duplication of the ENO1 gene locus in the tumor." (PMID 39239354, 2024). "Preclinical experiments have suggested that immunotherapy targeting ENO1 in MM can restore anti‐tumour immunity and enhance tumour‐killing activities." (PMID 39245797, 2024). "Analysis by histological subtypes and disease progression show that ENO1 was underexpressed in the tumours with better prognosis." (PMID 39483155, 2024). "With the unusual exposure of ENO1 on the surface of tumour cells, patients with solid tumours have been shown to develop autoantibodies to ENO1, the presence of which correlate with diagnosis of osteosarcoma as well as tumours in the lung and liver." (PMID 38473245, 2024). "By driving the expression of onco-immune modulatory genes, such as ENO1, MUC1, COL5A1, and IL11, FABP7 enhances tumor-associated immune suppression, particularly by facilitating the infiltration of immunosuppressive cell populations within TIME." (PMID 39596296, 2024). "In the case of aAb to phosphorylated ENO1, we cannot distinguish aAb that are induced by ENO1 overexpression in tumor tissues or by bacterial infection." (PMID 37910256, 2023).
tumor (continued). "Mechanistically, KIAA1429 promoted tumor progression and glycolysis via stabilizing ENO1 mRNA in a way dependent on m6A." (PMID 37807062, 2023). "The total protein levels of LTF, LCP1, AZU1, and ENO1 were all shown to be downregulated in tumor tissues." (PMID 37304069, 2023). "Overexpression of ENO1 counteracted the effects of KIAA1429 on tumor growth and metastasis in OC cells." (PMID 37807062, 2023). "After knocking down the levels of ENO1 mRNA, the migration, invasion, and proliferation abilities of tumor cells decreased." (PMID 37810778, 2023). "The expression of ENO1 can be activated by several glucose transporters and glycolytic enzymes that participate in tumor development." (PMID 37497003, 2023). "Taken together, these findings suggest that CAD-14 substantially inhibits the tumor growth via knock-out ENO1 in vivo." (PMID 37959729, 2023). "Our study focuses on the role of ENO1 together with lactic acid in the interaction between tumor cells and macrophages." (PMID 36614179, 2023). "Our data strongly suggested that ENO1 promotes tumor progression by acting as a downstream target of KIAA1429." (PMID 37807062, 2023). "The cytoplasmic portion of NMRAL2P can bind to the ENO1 protein, postpone ENO1’s breakdown, promote glycolysis, and provide extra energy to tumor cells." (PMID 37810778, 2023). "Small interfering RNA (siRNA) transfection and recombinant human ENO1 (rhENO1) stimulation were used to interfere with the interaction between tumor cells and macrophages." (PMID 36614179, 2023). "MTS, Transwell, and clone formation assays showed that NMRAL2P overexpression increased the viability, migration, invasion and proliferation of tumor cells, while ENO1 gene knockout partially counteracted this tumor promoting effect." (PMID 37810778, 2023). "Collectively, ENO1 orchestrated the IL-6 secretion of macrophages via tumor cell-derived lactic acid." (PMID 36614179, 2023). "Multivariate analyses have shown that overexpression of ENO1 can be a predictor of tumor progression." (PMID 36845730, 2023). "There should be a high level of lipids, especially triglycerides, in tumor cells, which further stimulates and promotes the expression of ENO1." (PMID 37731842, 2023). "Despite the fact that there are a great number of TLR4 activators in the TME, there is limited evidence supporting the link between tumor-derived paracrine ENO1 and TLR4 expression." (PMID 36614179, 2023). "Our research demonstrates that ENO1 is a tumor-promoting factor in OC, increasing cancer proliferation and metastasis." (PMID 37807062, 2023). "CPT1A regulates the expression and stability of its substrate proteins, such as S100A10 and enolase 1, through CPTase-independent lysine succinyltransferase activity, thereby promoting tumor cell growth, proliferation and migration." (PMID 37291333, 2023). "Emerging evidence demonstrates that ENO1 is also directly involved in tumor cell progression and metastasis." (PMID 37568802, 2023). "The results showed that tumor sizes were significantly smaller in ENO1 knockout mice than in control mice, indicating that ENO1 knockout reduced the tumorigenicity of PDAC cells." (PMID 36845730, 2023). "Among them, the actions of 6 tumor-suppressing proteins, ENO1, Ubiquitin C (UBC), Moesin (MSN), heat shock protein 90ab1 (HSP90ab1, aka HSP90β), Calreticulin (CALR), and Histone H4 (H4), have been documented with a proposed mechanism 12-14." (PMID 37056934, 2023). "Overexpression of ENO1 counteracted the suppression of KIAA1429 on aggressive characteristics of tumor cells, as shown in an in vivo tumor rescue experiment." (PMID 37807062, 2023). "ENO-1 promotes tumor cell progression via a plethora of mechanisms, including inducing angiogenesis, evading immune suppression and growth suppressors, and resisting cell death." (PMID 36768924, 2023). "ENO1 is a key regulator participating in the activation of macrophages and the promotion of tumor progression." (PMID 36614179, 2023).
tumor (continued). "Collectively, ENO1 promotes tumor cell migration and invasion by orchestrating IL-6 secretion of macrophages via a dual mechanism, thus forming a positive feedback loop to promote OSCC progression." (PMID 36614179, 2023). "In conclusion, ENO1 promotes tumor cell migration and invasion by orchestrating macrophage-derived IL-6 via secretion of lactic acid and extracellular ENO1, thus forming a positive feedback loop to promote OSCC progression." (PMID 36614179, 2023). "Enolase 1, encoded by ENO1, is a critical regulator of the glycolytic and effector activity of CD8+ tumour-infiltrating lymphocytes." (PMID 37267382, 2023). "Alpha-enolase (ENO1) takes part in the Warburg effect by promoting tumor cells absorb glucose and produce lactic acid and is involved in tumor malignant progression and chemotherapeutic resistance." (PMID 37007125, 2023). "ENO1 promoted the migration and invasion of tumor cells by facilitating the epithelial–mesenchymal transition (EMT) through macrophages." (PMID 36614179, 2023). "The effects of ENO1 on the migration and invasion of tumor cells were determined by wound-healing assay and transwell assay in vitro." (PMID 36614179, 2023). "It is now believed that METTL3 regulates the metabolic reprogramming of tumors by modulating the expression of glucose transporters (GLUTs), lactate dehydrogenase (LDHA) and enolase 1 (ENO1) in tumor cells." (PMID 37996892, 2023). "Alpha-enolase (ENO1), a key regulatory enzyme in glycolysis, promotes glucose uptake and lactic acid production by tumor cells." (PMID 36733504, 2023). "GO enrichment analysis of a TNBC tumor with elevated expression of ENO1 and FDPS revealed the highest enrichment in functional categories associated with the cell cycle and mitosis." (PMID 37190091, 2023). "Through comprehensive mass spectrometry-based proteomics analyses of iTSC-derived CM, it became evident that the enriched pool of tumor-suppressing proteins encompassed entities such as Enolase 1 (ENO1), Moesin (MSN), and Heat shock protein 90 (HSP90AB1)." (PMID 37894284, 2023). "The anti-tumor action of ENO1 and MSN was mediated at least in part by Mtdh, a prognostic marker that substantially reduces the survival rate of cancer patients." (PMID 36923539, 2023). "Functional recovery assays were carried out to further clarify the role of NMRAL2P and ENO1 in tumor promotion." (PMID 37810778, 2023). "Overall, these results indicated that ENO1 is an important mediator for promoting the EMT of tumor cells through macrophages." (PMID 36614179, 2023). "ENO1 orchestrated the IL-6 secretion of macrophages via tumor cell-derived lactic acid and the paracrine ENO1/Toll-like receptor (TLR4) signaling pathway." (PMID 36614179, 2023). "ENO1 contributes to tumorigenesis by promotion of tumor proliferation, inhibition of cancer cell apoptosis, invasion and metastasis of tumor cells." (PMID 36765367, 2023). "Previous research has established that the PTM of ENO1 plays an essential role in basic biological processes and is closely related to tumor progression." (PMID 35434271, 2022). "All in all, studies have evaluated the importance of ENO1 in sustaining the Warburg effect, hence validating its value as a therapeutic target for deterring tumor development." (PMID 35434271, 2022). "These newly identified tumor suppressors, such as extracellular Eno1, Hsp90ab1, Eef2, and vinculin, downregulated Kdm3a, a histone demethylase, as well as the downstream oncogenic genes 21-24." (PMID 35547745, 2022). "The results of our experiment revealed that 2-DG reversed the effect of ENO1 on EMT progression, suggesting that ENO1-mediated regulation of tumor proliferation, migration, and drug resistance is associated with energy metabolism." (PMID 36620599, 2022). "Circ-ENO1 promoted glycolysis and tumor progression in LUAD through the miR-22-3p/ENO1 axis, identifying circ-ENO1 as a promising treatment target for LUAD patients." (PMID 35434271, 2022).
tumor (continued). "α-enolase (ENO1) is a key glycolytic enzyme in catalyzing the conversion of phosphoglycerol to phosphoenol pyruvate, which is important for tumor proliferation, invasion, metastasis and adaption to hypoxic microenvironment." (PMID 36295613, 2022). "The results demonstrate that lncRNA-6195 is a tumor suppressor which inhibits tumor growth by binding to the substrate region of ENO1." (PMID 35154157, 2022). "Here, we review up-to-date articles and summarize the new findings that shed fresh insight on the relationship between ENO1 and tumor progression." (PMID 35434271, 2022). "In hepatocellular carcinoma, enhanced ENO1 expression increased with tumor metastasis and correlated positively with venous invasion." (PMID 35434271, 2022). "Tissues with tumor-node-metastasis (TNM) staging I-II showed lower ENO1 expression compared with those with TNM staging III-IV in CRC (P < 0.01)." (PMID 36620599, 2022). "Several glycolytic enzymes including ENO1 were found overexpressed in tumor cells subjected to hypoxia." (PMID 35204345, 2022). "In fact, C5aR1-positive neutrophils can secrete IL-1β and TNF-α to active ERK1/2 signaling, phosphorylate and stabilize WTAP, which can increase the m6A level of ENO1, and the up-regulated ENO1 can promote glycolysis, thus promoting tumor progression." (PMID 35022030, 2022). "In the cytoplasm, ENO1 is a key glycolytic enzyme in the production of ATP (adenosine triphosphate), thus its depletion would demobilize tumor activities." (PMID 35434271, 2022). "Special attention is focused on the role of ENO1 in tumor progression, the prospects of ENO1 as a cancer biomarker, and novel ideas in cancer treatments." (PMID 35434271, 2022). "Taken together, ENO1 is a crucial molecular target for tumor therapy, which has emerged to be a research hotspot in recent decades." (PMID 35434271, 2022). "Overall, our results revealed that ENO1 was abnormally overexpressed in BLCA, upregulation of ENO1 predicted unfavorable clinical outcomes and was significantly associated with tumor malignancy." (PMID 35836227, 2022). "We proposed that CCDC65 played the role of tumor suppressor by regulating the c-Myc/ENO1/AKT1 pathway." (PMID 35844805, 2022). "To access the mechanism of anti-tumor, anti-inflammatory actions of YS MSC CM, we selected five tumor suppressors (Hsp90ab1, calreticulin, histone H4, polyubiquitin C, and enolase 1) based on our previous whole-genome proteomics analysis." (PMID 35804814, 2022). "ENO1 level in 120 pairs of tumor tissues and adjacent normal tissues was examined by immunohistochemistry, and the correlation between ENO1 expression and prognosis was explored by survival analysis." (PMID 36620599, 2022). "An ex vivo analysis of Panc-1 cells derived from a liver metastasis (Panc-1/M) found higher surface expression of ENO1 compared with the primary tumour cells." (PMID 35204653, 2022). "ENO1 is involved inmultiple pro-tumorigenic and pro-glycolytic processes, such as but not limited to tumor growth, metastasis and migration." (PMID 35078505, 2022). "The findings suggest that the inhibition of ENO1 expression increases tolerance to hypoxia in tumor cells, which demonstrate slower cell growth, increased apoptosis, and a smaller tumor size." (PMID 35434271, 2022). "For instance, ENO1 in cytoplasm is involved in glycolysis pathway and aerobic glycolysis of certain tumor cells." (PMID 36295613, 2022). "ENO1 is thought to energetically feed tumor development and progression by supporting anaerobic glycolysis; however, its pro-tumorigenic role goes beyond energetic purposes." (PMID 35886909, 2022). "To study the mechanism of enhanced tumor growth after ENO1 activation in a hypoxic microenvironment, we determined the cell proliferation and apoptosis rates in each group of tumors." (PMID 36476328, 2022). "The ENO1 metabolically maintains the Warburg effect in tumor cells and its inhibition induces reactive oxygen species." (PMID 36077431, 2022).